PARP1 (poly(ADP-ribose) polymerase 1)
Diseases named in the same sentence as PARP1 in open-access papers (continued):
Sharing a sentence is not in itself a finding about the gene and the disease.
ovarian carcinoma (continued). "Data in the literature for ovarian cancer showed an inverse association between PARP1 and BRCA1 expression, supporting the hypothesis that loss or dysfunction of one crucial DNA repair pathway can be compensated by a “shift toward” and up-regulation of alternate DNA repair mechanisms." (PMID 29029467, 2017). "Therefore, PARP1 overexpression may constitute a specific epigenetic mark in BRCA-mutated ovarian cancer." (PMID 23442605, 2013). "Our present study is the first to analyze DNA methylation patterns in the PARP1 promoter region in BRCA-mutated ovarian cancer, showing that abnormal hypomethylation of this promoter, especially around the E26 transformation-specific (ETS) motif, may be responsible for PARP1 overexpression." (PMID 23442605, 2013). "In recent years, inhibitors of poly(ADP-ribose) polymerase 1 (PARP1) have revolutionised the therapy of ovarian cancer, particularly in tumours that have preexisting damage to their homologous recombination." (PMID 39862711, 2025). "Elevated PARP-1 levels were also found to drive increased ADP-ribosylation in ovarian cancers, with olaparib sensitivity relating to ADP-ribosylation levels." (PMID 40069561, 2025). "ADP-ribosylation also plays a crucial role in ovarian cancer research, with poly(ADP-ribose) polymerase 1 (PARP1) serving as the central enzyme." (PMID 41219748, 2025). "PARP inhibitors block the active site of PARP1 in BRCA-mutant ovarian cancer, disrupting ADP-ribosylation, inducing apoptosis in cancer cells, and extending progression-free survival." (PMID 41219748, 2025). "Overexpression of PARP1 has been reported in several malignancies, including breast, uterine and ovarian cancers, where it contributes to cell survival, mutagenesis and tumor progression." (PMID 40869324, 2025). "Interim analyses of an ongoing clinical trial (NCT02637934) evaluating [18F]PARP1‐inhibitor PET in ovarian cancer compared results of [18F]PARP1‐inhibitor PET with [18F]FDG PET in eight and 14 patients, respectively." (PMID 40923371, 2025). "In ovarian cancer, where PARP‐1 expression is correlated with a poor prognostic, its inhibition has been shown to induce oxidative stress, which mediates its antitumor effect." (PMID 39778077, 2025). "Both KAT6A LLPS and the interaction between KAT6A and PARP1 were enhanced in the PARPi‐resistant ovarian cancer cells." (PMID 38973255, 2024). "The ovarian tumor-derived sEVs delivered a CRSIPR/Cas9 system editing Poly (ADP-Ribose) Polymerase-1 (PARP-1) selectively to ovarian cancer cells to increase their chemosensitivity and produced synergic cytotoxicity when combined with chemotherapy." (PMID 38773978, 2024). "PARPi reduced the invasiveness and cell proliferation of ovarian cancer cells via PARP-1-mediated modulation of the NF-κB p65 subunit." (PMID 39201718, 2024). "Overall, these data indicate that APEX1 is essential for the LLPS of KAT6A and the interaction of KAT6A with PARP1 in PARPi‐resistant ovarian cancer cells." (PMID 38973255, 2024). "In another study, the knockdown of NEAT1 improved cisplatin response by increasing miR-770-5p and decreasing PARP1, demonstrating a novel treatment target for enhancing the efficacy of cisplatin in ovarian cancer cells." (PMID 38356722, 2024). "Collectively, these findings suggest that KAT6A sequesters PARP1 away from DNA break sites, impairing PARP1 trapping during PARPi treatment of PARPi‐resistant ovarian cancer cells." (PMID 38973255, 2024). "Instead of targeting DDX41 itself, we can target DDX41's SL partner, analogous to the case where PARP-1 inhibitors are used to treat BRCA1/2-mutated breast and ovarian cancer patients." (PMID 38348889, 2024). "PARP-1 knockdown in ovarian cancer cells reduced VEGF mRNA and protein secretion, hampering tubule formation of endothelial cells." (PMID 39201718, 2024).
ovarian carcinoma (continued). "A similar approach has been conducted in experimental glioma and ovarian cancer using PARP1 inhibition plus temozolomide and WEE1 inhibition plus carboplatin, respectively." (PMID 38475864, 2024). "When examining patient epithelial ovarian cancer tissue, it was found that 73.3% of a 60 patient cohort had overexpression of PARP1 when measured using immunohistochemistry." (PMID 39272943, 2024). "The interaction between KAT6A and PARP1 was increased in PARPi‐resistant ovarian cancer cells, as observed above; therefore, we further analyzed the relationship between KAT6A LLPS and the binding of the two proteins." (PMID 38973255, 2024). "Further analysis identified an interaction between KAT6A and PARP1 in ovarian cancer cells, and this interaction between KAT6A and PARP1 was confirmed in HEK293T cells." (PMID 38973255, 2024). "Analysis of PARP1/2 in ovarian carcinoma has been done thoroughly, and different studies have evaluated immunohistological PARP1/2 expression and its association with BRCA mutational status or survival and have found a positive correlation." (PMID 37525239, 2023). "This is the basis of PARP1 inhibitor target therapy for BRCA-mutated breast cancer and ovarian cancer." (PMID 37483616, 2023). "Further, HMGB3 promotes PARP inhibitor resistance of ovarian cancer through directly interacting with PARP1." (PMID 37328851, 2023). "Inhibitors of PARP1/2 are FDA-approved for the treatment of tumours with germline mutations in double strand break repair genes, such as BRCA-mutated breast and ovarian cancer." (PMID 36839682, 2023). "NAC is an antioxidant that inhibits PARP-1-mediated dysregulation of cell proliferation, highlighting a protective role for PARP-1 in augmenting the antioxidant capacity of ovarian cancer cells." (PMID 37351512, 2023). "These 11 significant hits include 2 flavonols (F2 and F3), 7 chalcones (C1, C2, C3, C6, C8, C11, and C12), a flavonoid analog (A3) and 1 FDA-approved drug (P1) known as Niraparib, which is a PARP-1 inhibitor notably prescribed for advanced ovarian cancers." (PMID 36651723, 2023). "Interfering with PARP-1 activity can also increase ROS levels in ovarian cancer cells, leading to DSB in the DNA." (PMID 37351512, 2023). "Niraparib is a potent and highly selective PARP-1/2 inhibitor that has shown promising efficacy in patients with relapsed ovarian cancer." (PMID 38021157, 2023). "Remarkably, COH34 is effective at killing ovarian cancer cells that are resistant to the PARP1 inhibitor." (PMID 35806303, 2022). "Overall, our results from RNA-seq and IHC suggest that PARP1 is highly expressed in BRCA1/2 mutation-associated breast and ovarian cancers." (PMID 36344544, 2022). "In studies of ovarian cancer, three PARP1 inhibitors, olaparib, niraparib, and rucaparib exploit synthetic lethality in platinum-sensitive, relapsed serous ovarian cancer." (PMID 35806303, 2022). "Additive anti-proliferation effect of LAE003 and Olaparib was also observed in three ovarian cancer cell lines with high PARP1 protein level." (PMID 35419627, 2022). "Currently, PARP1 inhibitors have emerged as one of the successful novel approaches to targeted ovarian cancer treatment." (PMID 35875162, 2022). "LncRNA NEAT1 overexpression sponged miR-770-5p and inhibited the expression of PARP1, leading to cisplatin resistance in ovarian cancer." (PMID 36105363, 2022). "LncRNA NEAT1 depletion abrogated the cisplatin resistance via modulation of miR-770-5p and PARP1 in ovarian cancer." (PMID 36105363, 2022). "In one study, ovarian cancer-derived EVs were loaded with plasmids expressing CRISPR/Cas9 targeting poly (ADP-ribose) polymerase-1 (PARP-1) to treat ovarian cancer." (PMID 35189894, 2022). "Olaparib, the inhibitor of PARP1, has become the first-line standard treatment for advanced ovarian cancer patients in clinics." (PMID 36230568, 2022). "Remarkably, multiple studies have confirmed that PARP1 inhibitors can improve poor prognosis in ovarian cancer." (PMID 35875162, 2022).
ovarian carcinoma (continued). "miR-519a-3p was demonstrated to suppress the growth, invasion, and migration via PARP1 in ovarian cancer, and miR-519a-3p served as a target of LINC01419 to repress the proliferation and metastasis of osteosarcoma cells via PDRG1." (PMID 35350655, 2022). "The loaded SKOV3-derived exosomes demonstrated better targeting to SKOV3 compared to epithelial cell-derived exosomes in a xenograft mouse model and suppressed the expression of PARP-1 and induced apoptosis in ovarian cancer." (PMID 35054611, 2022). "PARP1’s involvement in multiple DNA repair pathways make it an ideal gene target for treatment of drug-resistant ovarian cancer." (PMID 36551731, 2022). "Exosomes containing CRISPR/Cas9 reduced the formation of poly (ADP-ribose) polymerase-1 (PARP-1), causing ovarian cancer cells to die." (PMID 36364116, 2022). "In pre-clinical xenograft models of ovarian cancer, combination treatment with PARP1 inhibitors and navitoclax reduces tumour burden compared with PARP1 inhibitors alone." (PMID 34237321, 2021). "LncRNA NEAT1 contributes to DDP resistance of ovarian cancer cells by regulating PARP1 expression via miR-770-5p." (PMID 34512721, 2021). "In xenografted mice, CRISPR/Cas9 plasmid-loaded sEVs efficiently suppressed the expression of poly (ADP-ribose) polymerase-1 (PARP-1), inducing apoptosis in ovarian cancer and making the cells more sensitive to cisplatin." (PMID 34571921, 2021). "The log-rank test and KMplotter analysis showed that ovarian cancer patients with increased PARP1 protein expression had poorer overall five-year survival." (PMID 34620163, 2021). "In the current study, we analyze the associations between 19 SNPs of six BER-related genes (hOGG1, APE1, PARP1, FEN1, LIG3 and XRCC1) and ovarian cancer risk by genotyping method in 196 patients and 272 controls." (PMID 33391423, 2021). "Overexpression of SERCA2b reduced curcumin-induced PARP1 cleavage in ovarian cancer cells, suggesting its role in the development of ovarian cancer." (PMID 33925440, 2021). "IHC images showed the different expression of PARP1 in normal ovarian tissues and ovarian cancer tissues." (PMID 34620163, 2021). "Pharmacologic inhibition of PARP1 with PARPi enhanced the tyrosine 705 (Y705) phosphorylation of STAT3 (p-STAT3) in ovarian cancer cell lines, which was mediated by dePARylation." (PMID 34956861, 2021). "In December 2014, olaparib was approved in the European Union and United States for the treatment of advanced ovarian cancer with BRCA mutations, this marked the first clinical acceptance of the feasibility of PARP1 as an anti-tumor target and the SL theory." (PMID 34066020, 2021). "NEAT1 is overexpressed in cisplatin-resistant ovarian cancer cells and sponges miR-770-5P to upregulate the expression of poly adenosine diphosphate-ribose polymerase 1 (PARP1), which leads to chemotherapeutic resistance in cancer." (PMID 34660304, 2021). "The aim of this report was to assess the potential antitumor effects of three novel B-lactam-steroid alkylating compounds on human ovarian cancer cells, together with their potential to inhibit PARP1/PARP2 activity." (PMID 34440232, 2021). "We evaluated three newly synthesized B-lactam hybrid homo-aza-steroidal alkylators (ASA-A, ASA-B and ASA-C) for their PARP1/2 inhibition activity and their DNA damaging effect against human ovarian carcinoma cells." (PMID 34440232, 2021). "After intravenous injection of exosomes from SKOV3 human ovarian cancer cells (SKOV3-Exos) loaded with CRISPR/Cas9, they target and accumulate in SKOV3 tumors, inhibiting PARP-1 gene expression and subsequently inducing apoptosis of ovarian cancer cells." (PMID 34054927, 2021). "Comparatively, the BRCA1 mutated UWB1.289 cancer cells demonstrated a much lower PARP1 and a reduced PARP2 mRNA transcription than the other ovarian cancer cell lines tested (t-test, p < 0.001)." (PMID 34440232, 2021).
ovarian carcinoma (continued). "Of three PARP genes (PARP1–3) implicated in DNA repair, the highest expression of PARP1 was observed in germline BRCA1 carriers in both breast and ovarian cancers." (PMID 33525353, 2021). "It is known that PARP1 is altered in 1.12% of high-grade ovarian serous adenocarcinoma patients and in 1.05% of ovarian carcinoma patients." (PMID 33352723, 2020). "PARP-1 was first described in 1966 but its pivotal role for ovarian cancer was only recently discovered." (PMID 33036656, 2020). "In the present study, we used another PARP-1 inhibitor, namely, Olaparib, a drug already in use for patients with ovarian cancer, in the transgenic model of Huntington’s disease." (PMID 33066292, 2020). "Three PARP-1 inhibitors are already available in the clinic to treat BRCA-1 and BRCA-2 deficient breast and ovarian cancers through achieving synthetic lethality." (PMID 32579168, 2020). "It is interesting to note that various PARP1 inhibitors are in clinical trials; however, they have geared towards BRCA1/2 or DNA damage repair deficiency in breast and ovarian cancers." (PMID 32455851, 2020). "PARP-1 inhibitors have been widely studied as potential cancer therapeutics for breast and ovarian cancers." (PMID 32509471, 2020). "PARP-1 inhibitor has been approved for clinical treatments for several tumors, such as ovarian cancers, microsatellite unstable cancers and pancreatic cancers, with satisfactory clinical effects and safety." (PMID 32317937, 2020). "Particularly, one report indicates the efficacy of rucaparib, a PARP1 inhibitor, is positively correlated with HR capacity in HR competent ovarian cancer." (PMID 31291457, 2019). "We present in silico and experimental evidences (in vitro and in vivo) for Mortaparib as a first potential dual inhibitor of mortalin and PARP1 for treatment of cervical and ovarian cancers." (PMID 31856867, 2019). "As for epithelial ovarian cancers, the inhibition of PARP1 even became a promising targeted therapies." (PMID 31391118, 2019). "Olaparib is the first PARP1 and PARP2 inhibitor approved for treatment of refractory ovarian cancer harboring BRCA1 or BRCA2 mutation." (PMID 31554189, 2019). "FDA has approved PARP-1 inhibitors like olaparib, niraparib and rucaparib as monotherapy for BRCA-mutated breast and ovarian cancer patients." (PMID 31303961, 2019). "It was recently demonstrated that microRNA-222 (miR-222) can both increase PARP1 activity, and promote PARPi sensitivity in ovarian cancer cells." (PMID 30621214, 2019). "Since majority of DNA damage-induced PARylation is primarily mediated by PARP1, we examined PARP1 expression levels in these ovarian cancer cells." (PMID 30741937, 2019). "Currently, PARP1 inhibitors like olaparib, niraparib, and rucaparib are used to treat a number of malignancies including ovarian cancer." (PMID 31823815, 2019). "All PARP inhibitors developed in epithelial ovarian cancers are PARP1/2 inhibitors, while olaparib and rucaparib also inhibit PARP3." (PMID 31374917, 2019). "PARP1 was measured by Western blot in several ovarian cancer cell lines and FTE-187, immortalized fallopian tube epithelial cells." (PMID 29684820, 2018). "Correspondingly, depletion of NOX1 and NOX4 significantly rescued the growth inhibition of tumors formed by PARP1-depleted ovarian cancer cells." (PMID 29684820, 2018). "The difference between tumor xenografts formed by PARP1-depleted and proficient ovarian cancer cells is more pronounced." (PMID 29684820, 2018). "In this study, we assessed the effect of AZD1775 on endometrial and ovarian cancer cells in the presence of two DNA damaging agents, the PARP1 inhibitor, olaparib, and the chemotherapeutic agent, gemcitabine." (PMID 29783721, 2018). "We showed that PARP1 is highly expressed in specimens of high grade serous ovarian carcinoma and its activity is required for unperturbed proliferation of ovarian cancer cells." (PMID 29684820, 2018).
ovarian carcinoma (continued). "Recent studies showed that results of the treatment with platins and PARP1 inhibitors in breast and ovarian cancers are dependant on the correlation between the increased expression levels of some miRNAs and a decrease in BRCA1 expression." (PMID 29021870, 2017). "The clinically available PARP1 inhibitors have shown considerable efficacy, especially in the treatment of breast and ovarian cancers, in patients with hereditary deletions of the HR BRCA1/2 genes." (PMID 28820388, 2017). "A promising therapy with poly (ADP-ribose) polymerase 1 (PARP1) inhibitors has recently been widely studied in ovarian cancer patients." (PMID 29254167, 2017). "Rucaparib (AG-014669, PF-01367338, trade name: Rubraca, given orally), an FDA granted and recently approved PARP1-based drug for BRCA-mutant ovarian carcinoma patients, is indicated for therapy one line earlier than olaparib." (PMID 28991194, 2017). "Recently, olaparib, an agent that targets several PARP isoforms including PARP1, PARP2 and PARP3, has been approved for the treatment of ovarian cancer in patients harboring deleterious mutations of the BRCA1/2 genes." (PMID 28108739, 2017). "Elevated PARP1 expression has been detected in several tumor types including breast and ovarian cancer with a further rise in triple-negative breast cancer and BRCA1- or BRCA2-mutated cancers." (PMID 29228718, 2017). "The finding that niraparib decreased replication fork restart and increased genomic instability is consistent with the molecular mechanism of synthetic lethality in PARP1 inhibition in BRCA1 and 2-deficient breast and ovarian cancers." (PMID 28756516, 2017). "Research focused on PARP1 inhibitor olaparib in the context of breast and ovarian cancer uncovered multiple pathways of partial or complete resistance that were utilized by cancer cells." (PMID 29355244, 2017). "Induction of ATM phosphorylation and PARP-1 by the antagonists was shown in the ovarian cancer cells." (PMID 29184090, 2017). "Niraparib (MK-4827, given orally) is another well investigated PARP1 inhibitor approved by the FDA as a maintenance therapy drug with platinum-sensitive recurrent ovarian carcinoma." (PMID 28991194, 2017). "Inhibiting PARP1 in HR-deficient cells, such as the BRCA1- or 2-mutant breast and ovarian cancers, leads to an accumulation of DNA damage from replication fork collapse and ultimately cell death." (PMID 28756516, 2017). "Lastly, in ovarian cancer models, key proteins that coordinate recognition of DNA damage, ataxia-telangiectasia mutated (ATM) and PARP-1, were induced." (PMID 29184090, 2017). "The United States Food and Drug Administration (FDA) also approved olaparib as a PARP1/2-related drug against BRCA-defective ovarian carcinoma with three or more pro-chemotherapies." (PMID 28991194, 2017). "This makes PARP1 an interesting therapeutic target in the context of malignancies with deficient HR, such as BRCA1 and BRCA2 mutant breast and ovarian cancers." (PMID 27336789, 2016). "Poly (ADP-ribose) polymerase 1 (PARP1) [SwissProt:P09874], a protein that in recent years has been extensively studied in breast and ovarian cancer, is upregulated in the basal-like cluster." (PMID 27357824, 2016). "Based on a series of basic, preclinical and clinical studies, the Poly (ADP-ribose) Polymerase 1 (PARP1) inhibitor, olaparib, has recently been approved for use in ovarian cancer patients with BRCA1 or BRCA2 mutations." (PMID 25883215, 2015). "We screened three cohorts of patients with ovarian cancer, totaling 313 samples, and evaluated PARP1 protein expression by immunohistochemistry with further validation by western blotting." (PMID 26354718, 2015). "In recent years, encouraging results have been achieved by PARP-1 inhibitors in treating BRCA 1/2-related breast and ovarian cancers, and here we observed that a PARP-1 inhibitor also alleviates AML tumor load and prolongs survival in mice." (PMID 26314963, 2015).